RSAD2 (radical S-adenosyl methionine domain containing 2)
Diseases named in the same sentence as RSAD2 in open-access papers (continued):
Sharing a sentence is not in itself a finding about the gene and the disease.
RSAD2 also shares sentences with these, for which no sentence is quoted: glioma (2 papers); infectious disease (2); measles (2); rheumatoid arthritis (2); asthma (1); bacterial pneumonia (1); bovine respiratory disease complex (1); bronchiolitis (1); chronic lymphocytic leukemia (1); chronic rhinosinusitis (1); diabetes (1); diarrhoea (1); endometritis (1); endothelial dysfunction (1); Flavivirus Infections (1); H1N1 virus infection (1); Hepatitis (1); hepatitis B (1); immune diseases (1); leukemia (1); metabolic dysfunction-associated steatohepatitis (1); metastatic colorectal cancer (1); metastatic melanoma (1); pancreatic cancer (1); periodontitis (1); Pneumocystis infection (1); pneumonia (1); postpartum depression (1); prostate carcinoma (1); psoriasis (1).
A further 11 diseases each share a sentence with RSAD2 in 1 paper.